EGFR (epidermal growth factor receptor)
Diseases named in the same sentence as EGFR in open-access papers (continued):
Sharing a sentence is not in itself a finding about the gene and the disease.
tumor (continued). "Lnc-EGFR expression in Tregs was found to be strongly related to EGFR/Foxp3 expression and tumor development but inversely related to IFN-γ expression." (PMID 39257589, 2024). "It exerts its anti-tumor effects by binding to EGFR and c-MET on the tumor surface, thereby inhibiting the activation of their signaling pathways and binding to extracellular segments to promote receptor-antibody complex degradation." (PMID 38774882, 2024). "EGFRvIII is a tumor-specific protein in GBM that represents the predominant form of EGFR in tumors, with approximately half of the EGFR-amplified GBM cases expressing this variant." (PMID 39406966, 2024). "Radiotracers that target EGFR alongside integrin αvβ3 offer insights into both the tumor cells and their vascular support, providing a more comprehensive view of tumor biology." (PMID 39598465, 2024). "If using EGFR-TKI to inhibit EGFR, it can suppress PD-L1 expression and reactivate anti-tumor immunity in T cells." (PMID 38762484, 2024). "With the deepening of the research on tumor pathogenesis, molecular targeted therapy has become a hot spot, such as tyrosine kinase inhibitors (TKIs) of epidermal growth factor receptor (EGFR)." (PMID 38172304, 2024). "EGFR-TKIs can remodel the tumor microenvironment (TME) by increasing CD8+ T cell infiltration and the presentation of MHC class I and II molecules, reducing the infiltration and function of Tregs." (PMID 38402169, 2024). "EGFR is a member of the ErbB receptor family, known to be involved in CAFs-mediated promotion of tumor invasion and metastasis." (PMID 38347596, 2024). "Pulmonary delivery of EGFR (Epidermal Growth Factor Receptor)-targeted SPIO (Superparamagnetic Iron Oxide) nanoparticles improved tumor retention and significantly inhibited lung tumor growth through hyperthermic destruction of NSCLC." (PMID 39204164, 2024). "Western blot analysis of tumor lysates harvested on day 26 confirmed that αEGFR-E-P125A–treated tumors demonstrated decreased phosphorylation of EGFR at Y1069, FAK at Y397, and STAT3 at Y705 compared with controls." (PMID 38315147, 2024). "The tumor microenvironment and antigen escape remain challenges with EGFR as a therapeutic target as well." (PMID 39364321, 2024). "For NSCLC patients with both EGFR mutation and HER2 amplification, the combination of almonertinib and pyrotinib is a valuable therapy that can continuously reduce tumor burden and achieve long-term survival." (PMID 39184039, 2024). "Of note, we previously reported EPHA2 and EGFR to be elevated in the tumor cell compartment of PDAC tissues." (PMID 38650175, 2024). "Subsequently, they conducted co-culturing experiments by introducing MUC1-CAR-T cells and EGFR VIII-CAR-T cells to their respective tumor organoids, thereby verified the anti-tumorigenic effect of these two innovative CAR-T cell targets." (PMID 38443969, 2024). "Our data show that cetuximab and the corresponding cetuximab-ADC demonstrated similar cell binding properties and EGFR-dependent internalization into acidic compartments of tumor cells." (PMID 38772416, 2024). "It inhibits the growth of tumor cells and blood vessels by binding to epidermal growth factor receptor (EGFR) and stimulates immune cells to produce strong anti-tumor effects." (PMID 39014366, 2024). "We observed that EGFR knockdown inhibited tumor cell activity, migration and proliferation, thereby suppressing tumor growth." (PMID 39430754, 2024). "We anticipate that this engineering concept will be an important step forward to improve the tumor specificity of CAR T cells directed against EGFR-positive solid cancers." (PMID 38492569, 2024). "In terms of resectability, patients with resectable disease had a higher incidence of EGFR‐mutant tumor (33.1%) than those with unresectable disease (18.5%)." (PMID 38622869, 2024). "Reduction of EGLN3 expression in tumor cells suppresses EGFR internalization, resulting in its hyperactivation." (PMID 38928200, 2024).
tumor (continued). "The non-receptor phosphatase PTPN14, another PTPRK D2 domain interactor, functions as a tumour suppressor and has been suggested to regulate Rab5 to Rab7 endosomal maturation, impacting on EGFR signalling." (PMID 38904097, 2024). "While high recurrence rates due to acquired tumor resistance present a challenge to Epidermal Growth Factor Receptor inhibition, combination therapies, particularly with PI3K inhibitors, have shown improved treatment responses in pHGG patients." (PMID 39654184, 2024). "A low-affinity anti-EGFR mAb (KD: 3.4 × 10−7 M) was efficiently taken up by cancer cells but not normal cells, which resulted in sufficient efficacy against tumor cells, but low toxicity against normal keratinocytes." (PMID 38339219, 2024). "Active immunotherapy targeting EGFR aims to elicit potent anti-tumor humoral responses, which offer the advantage of generating a repertoire of specific anti-EGFR antibodies within the body." (PMID 39766327, 2024). "TERT directly regulates the transcription of numerous genes, including those involved in tumor growth, such as epidermal growth factor receptor (EGFR) and vascular endothelial growth factor (VEGF)." (PMID 39126110, 2024). "In the ex vivo study, the fluorescence images showed the strong fluorescence intensity of the EGFR Affibody–IR700Dye conjugate not only in the tumor but also in the liver and kidney." (PMID 38542206, 2024). "In this way, the drug works as an antagonist with antitumoral capabilities to potentially inhibit neoplasm growth in EGFR-overexpressing tumor cells and induce cell death." (PMID 39202551, 2024). "This engineered BiKE was shown to effectively activate NK cells and significantly enhance EGFR-specific tumor cell lysis compared to a BiKE constructed with wild-type B7-H6." (PMID 39911822, 2024). "CD109 is essential for tumor progression by regulating EGFR/Akt signaling, usually involved in inflammation-related pathways." (PMID 39990858, 2024). "89Zr-cetuximab was developed for in vitro and in vivo studies using tumor cell lines with varying EGFR expression levels." (PMID 39239273, 2024). "Initially, the use of EGFR inhibitors such as gefitinib demonstrated promising results in tumor regression and disease stabilization." (PMID 38921583, 2024). "EGFR plays a key role in tumor development and progression and has become an important target for cancer treatment." (PMID 38562672, 2024). "Cells in the high-scoring group activated most of the signaling pathways associated with tumor initiation and progression, including TGF-β, CCL, PTN, FGF, VEGF, and EGFR." (PMID 39456925, 2024). "Activation of MET, part of the tyrosine kinase family, promotes tumor cell growth, survival, migration, and invasion through activation of downstream oncogenic pathways in the setting of resistance to EGFR TKIs." (PMID 38276867, 2024). "These engineered T cells co-express an EGFRvIII-specific CAR with an EGFR-specific BiTE, thus combining high tumor specificity (conferred by the EGFRvIII-CAR) with complete tumor eradication (mediated by the EGFR-BiTE locally secreted in the tumor)." (PMID 38492569, 2024). "Because of all these observations, EGFR represents, in principle, a rational target for anti-tumor strategies." (PMID 38473265, 2024). "Studies using Ba/F3 cells, patient-derived cells, organoids, and xenografts with various Exon20ins demonstrated that amivantamab inhibits tumor growth by reducing EGFR-MET levels and enhancing immune response, indicated by increased IFNγ secretion." (PMID 39598385, 2024). "The FOXP3+ TIL density was increased in PD-L1-strong-positive tumor specimens before and after EGFR-TKI treatment compared with the corresponding PD-L1-negative or -low-positive tumor specimens." (PMID 38674427, 2024). "By leveraging information within the signatures, we discover that the HB-EGF/EGFR/MAPK axis represents a hub of tumor-stroma crosstalk, promoting the expression of CSF2 and LIF and favoring the recruitment of macrophages." (PMID 39262776, 2024).
tumor (continued). "Mice were i.v. inoculated with anti-EGFR ctrl- or Rapa-CD8CAR cells 5/6 weeks after inoculation of tumor cells, and then sacrificed 4 days after." (PMID 38467616, 2024). "EGFR overexpression or activation in CCA has been linked to poorer prognosis and aggressive tumor behavior." (PMID 38730642, 2024). "Monoclonal antibodies exert their inhibitory effects on tumor cell proliferation by binding to the extracellular ligand-binding region of EGFR, thereby preventing its binding to endogenous ligands and consequently inhibiting the EGFR signaling pathway." (PMID 39796003, 2024). "We discovered that each tumor has an average of two separate processes, and that, consistent with prior research, EGFR is a major core target in at least one of them in half of the tumors analyzed." (PMID 38229082, 2024). "Only one of the six heterozygotes identified had a cancer diagnosis at an early age: a LUAD-affected female diagnosed at age 44, with a somatic activating EGFR alteration in the tumor." (PMID 38252059, 2024). "Encouraged by the impressive specificity of MNB-Pyra Nbs for EGFR-overexpressing cells, the targeting ability of the conjugate was evaluated in tumor-bearing nude mice." (PMID 39138197, 2024). "Subsequently, it activates the positive feedback loop of the Wnt/β‐catenin signaling pathway, thereby promoting tumor progression and conferring resistance to EGFR‐TKIs." (PMID 38867713, 2024). "Specifically, the increase in membranous EGFR under dasatinib treatment, which indirectly indicates the regaining of sensitization to cetuximab, strongly correlated (r > 0.8) with the increased tumor uptakes." (PMID 39768978, 2024). "In vivo, experiments indicated the downregulation of EGFR mRNA and protein significantly in a xenograft tumor derived from TNBC cells." (PMID 39199788, 2024). "PERSEIDA was an observational, prospective study assessing cfDNA RAS, BRAF and EGFR mutations (using IdyllaTM) in first-line mCRC, RAS wild-type (baseline tumor-tissue biopsy) patients (cohort 2)." (PMID 38642257, 2024). "In, 2016, the FDA approved Atezolizumab as a therapy for patients with metastatic NSCLC who have experienced disease progression during or following platinum-containing chemotherapy, and if their tumor has EGFR or ALK gene abnormalities." (PMID 38384472, 2024). "Even after rectifying for stage and tumor size, right-sided CRCs, for example, have a worse prognosis and respond less to EGFR inhibitors." (PMID 39138146, 2024). "Moreover, the deletion of ARID1A in the tumor microenvironment activates cancer-associated fibroblasts and drives the proliferation and migration of lung cancer cells, but inhibits tumor cell autophagy and enhances the sensitivity of immunosuppressive therapy for EGFR-mutant lung adenocarcinoma." (PMID 38584203, 2024). "One study on IGF-1R expression in NSCLC found that treatment with IGF-1R TKIs exhibited significant anti-tumor activity in NSCLC cells with wild-type EGFR and KRAS." (PMID 38540176, 2024). "Similar to the previous findings, TFF1’s validation with a fold change of 2.8 confirmed its role in tumor cell invasiveness through EGFR signaling and G-protein-coupled receptor pathways." (PMID 39839775, 2024). "Cetuximab, the first targeted therapy approved to treat advanced CRC, is a monoclonal antibody that targets the epidermal growth factor receptor and inhibits downstream pathway activation to restrict tumor cell growth and proliferation." (PMID 39001533, 2024). "HER3 not only displays persistent signaling, but can also form heterodimers similar to EGFR and, through activation of several downstream signaling pathways, favors tumor cell survival and drug resistance." (PMID 39336976, 2024). "Better tumor regression was observed in groups treated with cetuximab (epidermal growth factor receptor-EGFR) and dasatinib (tyrosine kinase inhibitor) in combination compared to groups treated with only dasatinib." (PMID 38893132, 2024).
tumor (continued). "Non-small cell lung cancer (NSCLC) patients with EGFR mutations exhibit an unfavorable response to immune checkpoint inhibitor (ICI) monotherapy, and their tumor microenvironment (TME) is usually immunosuppressed." (PMID 39004699, 2024). "In conclusion, this study developed a simple and noninvasive method that combines tumor images, radiomics features, and clinical data extracted from pretreatment CT scans of NSCLC patients using deep learning models to predict EGFR mutations." (PMID 38195717, 2024). "Consistent with this conclusion, the promotion of autophagy using the mTOR inhibitor rapamycin enhanced the responsiveness of resistant tumor cells to EGFR tyrosine kinase inhibition." (PMID 39272847, 2024). "Current target therapy for BRAFV600E‐mutant tumours primarily focuses on competitively binding to the cell membrane's EGFR and blocking the intracellular RAF‐MEK signalling pathway." (PMID 39073010, 2024). "Prior studies have described the amplification, transcriptional upregulation, and over-expression of EGFR in cancerous states and delineated this a biomarker of tumor resistance." (PMID 38741774, 2024). "In vivo, tumors treated with dual anti-HER2/EGFR demonstrated decreased tumor hypoxia, when compared to single agent therapies." (PMID 38355949, 2024). "EGFR dysregulation can increase tumor angiogenesis, migration, and growth, contributing to poorer clinical outcomes in patients with GBM." (PMID 38927583, 2024). "As a consequence, it is well established that EGFR-targeting therapies lead to severe on-target/off-tumor toxicities; i.e., side effects due to recognition of EGFR in healthy tissues." (PMID 38492569, 2024). "This mutation impairs the binding of gefitinib’s 4-anilinoquinazoline core to the T790 residue, thereby enabling EGFR to continue signaling and promoting tumor cell proliferation." (PMID 39337496, 2024). "Activation of the EGFR pathway has been demonstrated to promote tumor cell growth, invasion, and angiogenesis, while also inhibiting apoptosis and inducing chemoresistance and radioresistance." (PMID 38576484, 2024). "EGFR, one of the receptor tyrosine kinase, plays a crucial role in tumor progression, resistance, and treatment failure." (PMID 39796008, 2024). "In this study, we developed and evaluated four machine learning models to predict EGFR mutation status in NSCLC patients using readily available clinical data, serum tumor markers, and CT imaging features." (PMID 39650554, 2024). "In vivo, we also observed a significant reversal of increased tumor metastasis in ADAMTS1-overexpressing Caki-1 cells when these cells were engineered to express shRNA targeting VCAN or the EGFR." (PMID 39333870, 2024). "In comparison, untreated tumors in groups II and III exhibited cells lacking differentiation and deeply stained granular nuclei, highlighting the effectiveness of the anti-EGFR-MPB nanocomposite in inhibiting tumor growth." (PMID 39525484, 2024). "Here, we generated 19 patient-derived xenografts (PDX) from 9 patients with multi-region and temporal sampling of osimertinib-resistant tumor tissue from patients with EGFR-mutant NSCLC." (PMID 38276867, 2024). "The resistance to anti-EGFR targeted therapy can rise also by the selection of tumor clones that use alternative pathways of signaling." (PMID 39000238, 2024). "Co-administration of excess EGF to block EGFR on normal tissues further decreased uptake in liver, kidneys and spleen but decreased tumour uptake (1.4% ID/g)." (PMID 38703297, 2024). "Hsa_circ_0000190 can similarly regulate epidermal growth factor receptor (EGFR)/extracellular regulated protein kinases (ERK) pathway activity in a manner beneficial to NSCLC tumor cells." (PMID 38440120, 2024).
tumor (continued). "Sunvozertinib inhibited EGFR ex20ins at half the inhibitory concentration (50%) in tumor cell lines expressing EGFR L8s8R, Exonl9del, L858R/T790M, and multiple ex20ins." (PMID 38774882, 2024). "How essential these interdependencies are is evident for a number of preclinical studies reporting enhanced tumor cell kill and radiochemosensitization when the epidermal growth factor receptor (EGFR) is inhibited simultaneously to β1 integrin." (PMID 38378518, 2024). "EGFR-T790M mutations also increase PD-L1 expression via PI3K/Akt, MAPK, and NF-κB signaling pathways, promoting tumor immune evasion." (PMID 38898505, 2024). "This suggests that cell–cell interactions in tumor tissues affect the efficacy of EGFR-targeting chemotherapeutic agents, which are commonly used for CRC treatment." (PMID 38182890, 2024). "Patients with BRAF V600E‐mutated GBM benefit from BRAF/MEK‐inhibition, whereas targeting EGFR alterations was unsuccessful due to poor tumor penetration, tumor cell heterogeneity, and pathway redundancies." (PMID 38899374, 2024). "Targeted therapy against HER2 alone is insufficient to generate strong and lasting anti-tumor response in NSCLC patients with EGFR mutant and HER2 amplification." (PMID 39184039, 2024). "The waterfall plot similarly showed a strong trend between PDC AUC values and the clinical tumor response to EGFR- or ALK-TKIs." (PMID 38398169, 2024). "This approach has been employed in studies targeting tumor cells via tumor-associated antigens such as HER2, EGFR, and EpCAM or immune cells through immunological receptors like CD20, CD19, CD8, CD4, and CD30." (PMID 39772246, 2024). "Another preclinical model involving human-induced pluripotent stem cell-derived teratoma xenograft model showed that EGFR806 CAR T cells, which are able to recognize low density EGFR, both selectively and effectively targeted EGFR-expressing tumor cells." (PMID 39364321, 2024). "In early HCC, β‐catenin is mainly localized in the cell membrane and forms a complex with multiple cadherin family members to promote tumor cell survival by enhancing the signaling of growth factor receptors, such as EGFR." (PMID 38318160, 2024). "In tumor glycolysis pathway, mutant EGFR promotes metabolic reorganization in NSCLC by increasing aerobic glycolysis and PPP, altering pyrimidine biosynthesis, and increasing monounsaturated fatty acid production." (PMID 38841622, 2024). "CDCP1 physically interacts with MET, particularly in contexts like squamous cell carcinoma, where this interaction contributes to resistance to EGFR inhibitors and promotes tumor growth, metastasis, and therapy resistance." (PMID 39769452, 2024). "Hub genes, including PLK1, CDK1, and EGFR, emerged as critical regulators of tumor proliferation and immune responses." (PMID 39457373, 2024). "Elevated EREG mainly activates EGFR signaling pathways and promotes tumor progression in HNSCC cells." (PMID 38945975, 2024). "Disitamab vedotin effectively targets HER-2, demonstrating potent anti-tumor effects while simultaneously inhibiting the epidermal growth factor receptor (EGFR) pathway." (PMID 39886664, 2024). "This metabolic shift, characterized by increased glycolytic activity and lactate production, can lead to further modification of the tumor microenvironment, resulting in resistance to EGFR-TKI therapy." (PMID 38689087, 2024).